CCK (cholecystokinin)
Diseases named in the same sentence as CCK in open-access papers (continued):
Sharing a sentence is not in itself a finding about the gene and the disease.
diabetes (26 papers, 2015 to 2026). "The major premise for associating CCK with diabetes is, nevertheless, the expression of CCK receptors and peptides as well as the sister hormone gastrin in pancreatic islets." (PMID 40557463, 2025). "An association between gastrin/CCK peptides and islet-cell functions (and hence a role for these peptides in diabetes therapy) has been discussed and examined in the last decades." (PMID 31853211, 2019). "Thus, it is likely that increased cholecystokinin octapeptide content and/or activity in diabetes might cause pathological changes in nociceptive transmission in primary afferent neurons." (PMID 38927539, 2024). "Moreover, CCK has recently been shown to exert important beta-cell proliferative and anti-apoptotic effects, which might counter beta-cell loss in diabetes." (PMID 34054734, 2021). "Regarding intestinal CCK secretion in diabetes, a reduced postprandial CCK response to low‐fat meals has been observed in patients with type 2 diabetes." (PMID 40557463, 2025). "Such difference renders it likely that meal‐induced CCK secretion contributes to the increased postoperative incretin effect, which in 80% of the bypassed patients reduces or eliminates type 2 diabetes mellitus." (PMID 40557463, 2025). "Our group was the first to report that a gastrointestinal hormone, cholecystokinin (CCK-8), which delays the rate of gastric emptying in patients, had the potential to treat diabetes by lowering postprandial glucose levels." (PMID 39219790, 2024). "Collectively, our findings advocate for verapamil’s reevaluation as a multifaceted agent in diabetes therapy, highlighting its novel function in CCK upregulation alongside enhancing β-cell proliferation, glucose sensing, and oxidative respiration." (PMID 38891081, 2024). "Hemokinin-1 was suggested to be involved in the transmission of diabetes-induced mechanical allodynia, albeit weakly compared to cholecystokinin octapeptide and nociceptin/orphanin FQ." (PMID 38927539, 2024). "At the level of the pancreatic beta-cell an important GLP-1/CCK intra-islet loop has also been described that helps protect against beta-cell apoptosis, with obvious benefits for diabetes." (PMID 34054734, 2021). "So far, modified CCK and gastrin peptides are being examined as potential drugs for therapy of type 1 as well as type 2 diabetes mellitus." (PMID 31853211, 2019). "Studies have shown that changes in CCK expression or a reduction in a > number of CCK receptors contributes to various gastrointestinal and metabolic diseases such as diabetes mellitus, gall stone disease and irritable bowel syndrome." (PMID 24854048, 2015). "The pharmacological methods currently used to treat diabetes could be supported by the application of CCK agonists." (PMID 39408213, 2024). "Furthermore, PC has been found to have a direct inhibitory effect on the progress of inflammation and can quench appetite by inducing the liberation of cholecystokinin (CCK) and leptin; such action of PC may have an anti-obesogenic result and provide some level of protection against diabetes." (PMID 39932911, 2025). "The peak of postprandial hyperglycemia was lower in the patients with diabetes whose gastric emptying was lower, and GLP-1 and CCK were secreted after a meal in the patients with type 1 diabetes." (PMID 39899133, 2025). "Transgenic mouse that expresses CCK in the β-cell in the lean state showed increased β-cell area even in old age, resisted STZ-induced diabetes and had reduced β-cell apoptosis." (PMID 28824543, 2017). "In this review, I analyse the FDA approval of natural peptides, as well as engineered peptides for diabetes treatment, growth-hormone-releasing hormone (GHRH), cholecystokinin (CCK), adrenocorticotropic hormone (ACTH), and α-melanocyte stimulating hormone (α-MSH) peptide analogues." (PMID 38540684, 2024).
diabetes (continued). "In diabetes, pain sensitivity is enhanced by cholecystokinin octapeptide, and the mechanism is mediated by CCK-B, but not CCK-A, receptors located on the primary afferent neurons." (PMID 38927539, 2024). "Thus, the intestinal CCK synthesis and secretion are apparently not changed to any significant extent in diabetes." (PMID 40557463, 2025). "CCK peptides have evoked some interest in diabetes research, not least because CCK, in itself being a minor incretin, may potentiate the effect of major incretins such as GLP‐1 and GIP." (PMID 40557463, 2025). "While the polygenic Otsuka Long-Evans Tokushima Fat rat (OLETF) also exhibits a prediabetic phase similar to the ZDSD rat, OLETF rats develop diabetes due to a lack of the cholecystokinin (CCK)-1 receptor, leading to hyperphagia and increased glucose production." (PMID 37233701, 2023). "In addition, CCK signaling may contribute to the pathophysiology of diabetes, as short-term HFD consumption abolished the ability of intralipid or low levels of exogenous CCK-8 (35 pmol/kg/min) to lower glucose production in rats during a glucose clamp." (PMID 35474341, 2022).
gallstones (23 papers, 2007 to 2025). Solid crystalline precipitates in the biliary tract, usually formed in the gallbladder, resulting in the condition of cholelithiasis. "Obviously, daily intravenous infusion of CCK-8 can enhance complete gallbladder emptying, thus eliminating the inevitable risk of biliary sludge and gallstone formation." (PMID 33260332, 2020). "It has been reported that PPIs could reduce the release of cholecystokinin, which might diminish gallbladder motility, thereby causing the formation of gallstones." (PMID 40139907, 2025). "Therefore, it is postulated that the exclusion of the duodenum leads to changes in the pattern of cholecystokinin secretion, resulting in decreased gallbladder contraction and an increased risk of gallstone formation." (PMID 34996411, 2022). "Previous research reported that leptin-deficient or leptin-resistant obese mice exhibited decreased gallbladder responses to NPY and CCK compared with control mice with normal leptin metabolism, suggesting that leptin dysregulation is associated with gallbladder motility and gallstone formation." (PMID 29088261, 2017). "Total parenteral nutrition and enteral tube feeding impair gallbladder contraction by decreasing the secretion of CCK and are involved in the formation of gallstones." (PMID 40165929, 2025). "In particular, hyperinsulinemia reduces gallbladder motility induced by CCK and increases the incidence of gallstones." (PMID 29088261, 2017). "Gallbladder dysmotility accerelates gallstone formation and gallbladder contraction depends on cholecystokinin (CCK) and its receptor (CCK-1R)." (PMID 17547774, 2007). "This may lead to a decrease in plasma CCK levels, impairing gallbladder contraction and promoting gallstone formation." (PMID 40182307, 2025). "Gallstones may be developed in obese individuals due to impaired gallbladder motility for decreased sensitivity to cholecystokinin." (PMID 39574912, 2024). "Although the mechanism was not fully understood, the change in the pattern of cholecystokinin secretion according to the type of subtotal gastrectomy might have a role in gallstone formation." (PMID 37627910, 2023). "Notably, there is more rapid evolution from solid cholesterol crystals to gallstones in CCK knockout mice than in other mouse models of cholesterol gallstones on the same lithogenic diet, which highlights the importance of impaired gallbladder emptying." (PMID 33260332, 2020). "In PPG, the physiological reconstruction without vagotomy maintains the contraction of Oddi sphincter and secretion of cholecystokinin, whereas the risk of gallstones formation was decreased in the PPG group but not significantly in comparison with DG." (PMID 32641052, 2020). "The pathophysiology of gallstone information after gastrectomy was regarded as vagal nerve resection, nonphysiological reconstruction of the gastrointestinal tract and decreased secretion of cholecystokinin." (PMID 31117975, 2019). "Thus, further studies validating our findings and testing the correlation between the presence gallstones, CCK, and AP after VSG and RYGB are warranted." (PMID 30206217, 2018). "CCK promotes gallbladder contraction and the release of pancreatic enzymes and may be responsible for the higher risk of AP in VSG patients with gallstones compared to RYGB54,55." (PMID 30206217, 2018). "In gastric operations, reconstruction of the digestive tract may decrease passage of food through the duodenum, which probably decreases cholecystokinin secretion and reduces gallbladder motility, facilitating gallstone formation." (PMID 30092786, 2018). "Notably, sleeve gastrectomy (SG) is associated with a more significant increase in CCK compared to RYGB, which may explain the lower incidence of gallstones following SG." (PMID 40182307, 2025).
gallstones (continued). "By contrast, repeated gallbladder contraction and emptying as stimulated by supra-physiological doses of CCK-8 could improve gallbladder motility by restoring gallbladder contractility and subsequently prevent the formation of biliary sludge and gallstones in patients receiving TPN." (PMID 33260332, 2020). "Cholecystectomy has been shown to be capable of increasing the serum levels of cholecystokinin and secretin, and it is suggested to measure their serum levels before and after the removals of gallstones to ascertain whether this alteration is related to increased risk of prostate cancer." (PMID 32120816, 2020). "Also, radical gastrectomy usually involves Billroth II and Roux-en-Y techniques, which eliminate food passing through the duodenum, and may reduce secretion of cholecystokinin and gallbladder activity, promoting cholestasis and gallstone formation." (PMID 31088424, 2019). "Ultimately, gallbladder dysmotility, particularly in patients with elevated EF on HIDA-CCK (cholecystokinin) imaging, can mimic classic biliary colic despite lacking gallstones or wall abnormalities." (PMID 41018449, 2025). "In addition to the same gallbladder phenotype, i.e., impaired gallbladder emptying in both CCK and CCKAR knockout mice, the identical evolutionary sequences from solid cholesterol crystals to gallstone formation are found in both strains of knockout mice." (PMID 33260332, 2020).
pancreatic cancer (22 papers, 1985 to 2025). "It is therefore possible that the pancreatic tumour growth associated with CCK expression can be attributed to the capacity of CCK to promote macrophages to adopt a pro-tumour, M2 phenotype." (PMID 34572888, 2021). "In pancreatic cancer, CCK expression was also found to associate with larger tumors and a higher incidence of metastasis." (PMID 26700819, 2016). "A high fat intake affects pancreatic cancer risk by stimulating cholecystokinin (CCK) release, which, in rodents, increases susceptibility to carcinogens and causes acinar cell hyperplasia, followed by the development of pancreatic carcinomas." (PMID 15685231, 2005). "CCK-BRs are present on activated pancreatic stellate cells or fibroblasts, and interruption of this signaling pathway decreases the genes implicated in epithelial to mesenchymal transition, invasion, and metastases in pancreatic cancer." (PMID 41373844, 2025). "If the hypothesis that the promoting effect of dietary fat on pancreatic carcinogenesis is mediated via CCK is correct, this could partly explain the reduced pancreatic cancer risk associated with both specific and total saturated FAs." (PMID 15685231, 2005). "Animal experiments suggested that fatty acids in chyme excited cholecystokinin releasing when entering the duodenum, which increasing the pancreatic susceptibility to carcinogens as well as causing the hyperplasia of acinar cell, therewith the pancreatic carcinomas development in rodents." (PMID 26110621, 2015). "Although other researchers have described the cross-communication between PSCs and pancreatic cancer cells, this work is unique because the focus is on the importance of the CCK-BR signaling pathway mediating this communication." (PMID 41373844, 2025). "Inhibition of the CCK-BR signaling pathway in the pancreatic cancer fibroblasts has the potential to improve treatments for patients with pancreatic cancer." (PMID 41373844, 2025). "CCK was also identified as a target of the vasodilator, diazoxide, which is used to manage hypoglycemia due to pancreatic cancer or other conditions." (PMID 40034430, 2025). "In reciprocal, to study how the CCK-BR signaling pathway influences the cross-communication and growth of pancreatic cancer cells, the mT3 cancer cell number was counted after co-culture for 5 days with wild-type or CCK-BR-KO PSC." (PMID 41373844, 2025). "When CCK-BRs are stimulated, the PSCs become activated and produce collagen, the major component of the fibrosis in chronic pancreatitis and pancreatic cancer." (PMID 41373844, 2025). "Using the transwell cell culture technique and application of conditioned media to pancreatic cancer cells from PSCs, we confirmed that the CCK-BR pathway is involved in the cross-communication between the cancer cells and the PSCs." (PMID 41373844, 2025). "This study shows that the CCK-BR targeted NP also can deliver siRNA payload and decrease pancreatic cancer growth and metastases, and improve survival in an immune competent mouse model." (PMID 36614194, 2023). "In these series of experiments, we examined the effects of CCK-BR targeted NPs to improve survival and decrease metastases in athymic nude mice bearing orthotopic human pancreatic cancer." (PMID 36614194, 2023). "In vitro cultures of pancreatic cancer cells revealed that cholecystokinin (CCK8) increased CXCL10 levels through the regulation of the NF-κB activation." (PMID 34835155, 2021). "CCK-BRs are over-expressed in pancreatic cancer and activation stimulates growth in cell culture and in animal models." (PMID 34638432, 2021). "High-fat diet enhances pancreatic cancer progression through elevation in cholecystokinin (CCK) levels." (PMID 32370075, 2020). "The autocrine production of gastrin and CCK are important for stimulating pancreatic tumor cell growth." (PMID 32210918, 2020).
pancreatic cancer (continued). "Increased expression of gastrin and/or CCK were observed in human gastric adenocarcinoma, colorectal carcinoma, and pancreatic cancer, over that of the corresponding normal tissues, indicating potential roles of these peptides in promoting carcinogenesis." (PMID 32210918, 2020). "Recently, cholecystokinin antagonists were found to potentiate the effects of immune checkpoint inhibitors at impairing the growth of pancreatic tumors in vivo." (PMID 30008698, 2018). "The gastrointestinal peptides gastrin and cholecystokinin (CCK) have been found to stimulate the growth of several human pancreatic cancer cell lines in culture and pancreatic xenograft rodent models." (PMID 28634650, 2017). "The pancreatic cancer cells produced both CCK and gastrin, however the CCK level was lower than the gastrin." (PMID 23077482, 2012). "The role of the pancreaticotrophic hormone cholecystokinin (CCK) in modifying the pancreatic response to carcinogen has been examined in the hamster-nitrosamine pancreatic cancer model." (PMID 3966964, 1985). "We hypothesized that disrupting CCK-BR function shifts PSCs to a more quiescent phenotype and reduces their pro-fibrotic and tumor-supportive activity to decrease growth of pancreatic cancer." (PMID 41373844, 2025). "We further studied whether the CCK-BR targeted NP could deliver the murine KrasG12D siRNA payload to an immune competent mouse model with an established orthotopic syngeneic pancreatic tumor." (PMID 36614194, 2023). "Neuropeptides like bombesin, cholecystokinin, neuromedin N, neurotensin (NT), gastrin-releasing peptide and pituitary adenylate cyclase activating peptide stimulate growth and/or other cellular functions in various tumor types, including pancreatic cancer." (PMID 24212612, 2011). "We hypothesized that interference with the CCK-BR signaling pathway would shift PSCs to a more quiescent phenotype and reduce their pro-fibrotic and tumor-supportive activity to decrease the growth of pancreatic cancer." (PMID 41373844, 2025). "Besides adipokines, a leptin‐independent mechanism suppressible by weight loss has been demonstrated in leptin‐deficient obese mice, in which an aberrant expression of the intestinal peptide hormone cholecystokinin in pancreatic beta cells enhances pancreatic cancer growth." (PMID 40129249, 2025). "Furthermore, the decreased pancreatic cancer growth in mT3 cells with co-culture or with conditioned media from the knockout PSCs suggests that elimination of the CCK-BR signaling pathway interrupts paracrine mechanisms of communication or extracellular vesicles released from the PSC." (PMID 41373844, 2025). "Interruption of the CCK-BR signaling pathway with proglumide not only inhibits the proliferation of pancreatic cancer epithelial cells and tumors but also decreases the function of activated PSCs, thus providing a two-for-one hit therapeutic for pancreatic cancer." (PMID 37345148, 2023). "EGF and neuropeptides like bombesin, cholecystokinin, neuromedin N and NT may act as growth factors and stimulate proliferation on the one hand and/or affect other cellular functions in different tumor cell types, including pancreatic cancer, on the other hand." (PMID 24212612, 2011). "Although cholecystokinin (CCK) has not been associated with the risk of BC, it has been reported that it affects the proliferation of pancreatic cancer cells." (PMID 35115550, 2022). "While down-regulation of gastrin inhibited growth of pancreatic tumor, change in the CCK level did not affect the tumor growth." (PMID 23077482, 2012). "The goal of this work is to examine the role of the CCK-BR molecular and protein signaling pathways in activated pancreatic stellate cells and determine how interruption of this pathway can decrease the cancer-PSC cross communication and growth of pancreatic cancer." (PMID 41373844, 2025). "Importantly, CCK-KO mice or pancreatic tumors that lack CCK receptors are not affected by dietary fat." (PMID 32370075, 2020).
pancreatic cancer (continued). "A local regulatory mechanism through gastrin and CCK2R, but no CCK mechanism, might be involved in pancreatic carcinoma." (PMID 32210918, 2020). "The role of endogenous cholecystokinin (CCK) in human pancreatic cancer is not clear." (PMID 23077482, 2012).
depression (21 papers, 2012 to 2026). "Together, these results demonstrate that both the genetic and behavioral models of depression are associated with impairment in AMPAR signaling in CCK cells." (PMID 33742167, 2021). "Patients with major depression showed increased CCK levels in cerebrospinal fluid." (PMID 40034430, 2025). "Other neuropeptides with lower expression in depression are somatostatin (SST) and cholecystokinin (CCK)." (PMID 33589676, 2021).